IL13 (interleukin 13)
Diseases named in the same sentence as IL13 in open-access papers (continued):
Sharing a sentence is not in itself a finding about the gene and the disease.
tumor (continued). "On the other hand, Th2 cytokines like IL-4 as well as IL-13 can promote M2 polarization of macrophages, which exert anti-inflammatory, tumor promoting as well as parasite clearance effects." (PMID 35876627, 2022). "In some cancers, including breast, gastric and pancreas Th2 cells and associated cytokines (IL‐4 and IL‐13 and TSLP) contribute to tumour progression." (PMID 35344301, 2022). "NAFLD HCC patients had increased levels of IL-13, which can activate myeloid-derived suppressor cells and promote tumor progression by inhibiting cancer immunity." (PMID 35636146, 2022). "M2 macrophages are derived from M1 activation by factors such as IL-4 and IL-13 and have the potential to suppress immune responses, promote angiogenesis, tissue repair and promote tumor growth." (PMID 35546682, 2022). "Recent study has found that ILC2s in human and mouse CRC express PPARγ, which maintains ILC2 secretion of IL-5 and IL-13 and the pro-tumor effect of ILC2s." (PMID 35720302, 2022). "Conversely IL-4, IL-10 and IL-13 secreted by tumor or stromal cells can stimulate conversion of M0 to pro-tumor M2 macrophages." (PMID 36253762, 2022). "In line with our data, BM-derived myeloid cells activated by IL-4/IL-13 upregulated lymphatic-specific markers Lyve-1 and stabilin-1 in several tumor models." (PMID 35442077, 2022). "NKT1 is antitumor, while NKT2 is primarily tumor-promoting.IL-13 produced by NKT2 induces MDSC to produce TGF-β, which inhibits the anti-tumor immune response mediated by CD8+T cells." (PMID 35874717, 2022). "In line with the role of polarized MIL4/IL13 macrophages in providing an anti‐inflammatory and tumor‐promoting microenvironment, we propose that the proteins in this postulated network are involved in these processes." (PMID 35811571, 2022). "In clinical studies, it has been reported that tumor-activated ILC2s secreted IL-13 to induce M-MDSCs and support tumor growth, whereas ATRA treatment reversed the increase of ILC2-MDSCs in AML." (PMID 36172164, 2022). "Mechanistically, ILC2-derived IL-4 and IL-13 in response to IL-25 signaling activated tumour M-MDSCs derived from Apc1322T/+ mice to express Arginase 1 (Arg1) and suppress CD8+ T cells." (PMID 36263033, 2022). "Th17 cells are generated by tumor-derived IL1β and IL13, and accumulate in tumor tissues in response to various chemokines, including CCL2, CCL5, CCL20, CCL17, CCL22, and MIF, which are produced from tumor cells." (PMID 36211375, 2022). "Adoptive transfer experiments further confirmed that ILC2-derived IL-13 promotes immunosuppressive tumor M-MDSCs and reduces IFNγ+ T cells." (PMID 35658010, 2022). "It has been acknowledged that Th2 cells induce macrophages polarized to pro-tumor M2 phenotype through the secretion of IL-4 and IL-13." (PMID 36564797, 2022). "For instance, NKT II cells produce IL-13 in response to tumor growth, resulting in the excretion of TGF-beta from myeloid cells that inhibits cytotoxic T cell-mediated tumor immunosurveillance in several mouse tumor models." (PMID 35163235, 2022). "IL-13-LCL-SIM monotherapy induced an upregulation in the expression of VEGF, presumably secreted by tumor cells as a compensatory mechanism for direct targeting of pro-angiogenic macrophages by IL-13-conjugated liposomes." (PMID 35450036, 2022). "It has been observed that IL-4 in combination with IL-13 induces macrophages to support tumor survival by creating an immunosuppressive environment and enhancing tissue repair." (PMID 35884700, 2022). "M2-polarization is indicated by Th2 cytokines such as IL-4 and IL-13 and leads to macrophage functionalization in the context of anti-inflammatory processes, tissue repair, and immunoregulatory and tumor-promoting processes." (PMID 35563052, 2022). "Compared to virus-specific Th1 cells, this tumor-specific CD4+ T cell state differentially expressed genes associated with Th2 cells, including Igfbp7, Ccl1, Ccr8, and Il13, and downregulated Th1-associated genes, including Ccl5 and Ly6c2." (PMID 35829695, 2022).
tumor (continued). "Similar antitumor activity has also been described in lung ILC2s, as IL-33-activated ILC2s produce cytokines IL-5 and IL-13, recruiting eosinophils and DCs to the tumor site, respectively, which limits tumor growth and invasion." (PMID 35409105, 2022). "IL-13, structurally similar to IL-4, plays a role in tumor proliferation and metastatization and is considered a Th-2-derived protein." (PMID 35062739, 2022). "For example, high secretion of IL-13 negatively correlates with tumour thickness in both vehicle and 1,4-dihydroxy quininib treated tumours." (PMID 36698840, 2022). "Here, we investigated the pharmacological effects of GB-13, a novel tumor-specific immunotoxin that contains an engineered mutant of human IL-13 fused to a cytotoxic PE molecule." (PMID 35631512, 2022). "In cancer, the stimulation of ILC2s secreted by macrophages through IL‐33 induces the secretion of IL‐13 and IL‐5, which favour tumour progression." (PMID 35344301, 2022). "On the contrary, Th2 cells are associated with anti-inflammatory response, immunoglobulin E, and eosinophilic responses by IL-4, IL-5, and IL-13 secretion and the activation of TAMS and, therefore, are associated with tumor progression." (PMID 36142615, 2022). "On the contrary, the M2-like macrophages are activated by the type 2 T helper cell (Th2) cytokines such as IL-4, IL-10 and IL-13, and exhibit promoting tumor capacity." (PMID 36518756, 2022). "IL-4 and IL-13 are polarized to the M2 macrophage phenotype and support angiogenesis to drive tumor progression and recruit regulatory cells (Tregs)." (PMID 35800989, 2022). "S9G), demonstrating that ILC2-derived IL-4 and IL-13 promoted the suppressive functions of tumor M-MDSCs." (PMID 35658010, 2022). "Th2 cells exerts their anti-tumor property by recruiting eosinophils through the expression of IL-4 and IL-13." (PMID 35155430, 2022). "IL-4 and IL-13 are believed to carry out abundant functions in tumour cells through several pro-oncogenic pathways involving signal factors such as STAT3, STAT6, PI3K/Akt, and ERK1/2." (PMID 35409019, 2022). "A main factor of type II NKT cells-mediated tumor immunosuppression is the increased production of IL-13 and IL-4 cytokines, which tilt immune response mainly toward the Th2 type with pro-tumor functions." (PMID 36119047, 2022). "M2 TAMs secrete pro-tumor factors (such as IL-4, IL-6, IL-10, IL-13, EGF, and VEGF), while the tumor suppressor M1 TAMs expresses anti-tumor factors (such as IL-12, the major histocompatibility complex (MHC) class II, and TNF-α)." (PMID 36358823, 2022). "IL-4 and IL-13 cytokines are the established inducers of Th2 response, and overexpression of their receptors on tumor cells can be targeted by cancer therapies." (PMID 35450036, 2022). "M1 macrophages (CD86+ and CD80+) release pro-inflammatory cytokines (e.g., IL-6, IL-12, TNF-α) to play an anti-tumor role, while M2 macrophages (CD206+) release pro-tumor cytokines (e.g., IL-4, IL-10, IL-13) to promote tumor progression and metastasis." (PMID 35432300, 2022). "Although these TNBC-induced TAMs exhibit a differential gene expression profile, their tumor-promoting effects were similar to those of M2 macrophages polarized by IL-4 and IL-13." (PMID 35960749, 2022). "NK cells secrete a wide variety of anti-tumor cytokines such as IL-10, IL-5, IL-13, GM-CSF, IFN-γ, TNF-α." (PMID 36253762, 2022). "Local signals IL-13, IL-6, and IL-10 in the tumor microenvironment were reported to polarize macrophages into protumoral M2-like cells, which was in line with the results of flow cytometry." (PMID 35154567, 2022). "IL-13 modulates the proliferation and status of lymphocytes and has been explored in tumor research." (PMID 34600547, 2021). "In the TME, the presence of CAFs and their secretion of chemokines and cytokines such as CCL2, CCL5, CCL17, IL-1, IL-6, IL-13, and IL-26 can favor a tumor-promoting Th2 and Th17 immune response, at the expense of tumor-protective Th1 responses." (PMID 34663337, 2021).
tumor (continued). "On the contrary, TAMs (M2-like) polarized by IL-4 and IL-13 play the opposite immunosuppression and pro-tumor function in the TME." (PMID 33738286, 2021). "While IL-13 signalling in CRC and other tumour types has been associated with a poor prognosis, the role and function of ILC2-derived IL-5 are still poorly understood." (PMID 33535624, 2021). "The expression of EPHB2, IL-13, MAP2, RPN2, and TRAF5 was correlated with microsatellite instability (MSI), while the expression of IL-13, RPN2, and TRAF5 was related to tumor mutation burden (TMB)." (PMID 33937013, 2021). "IL-4/IL-13-polarized MDMs effectively suppressed ESO-T-cell-mediated killing of A375-A2-ESO tumor cells; this immunosuppressive effect was largely alleviated by phenelzine treatment during MDM polarization." (PMID 34112755, 2021). "Conversely, M2 macrophages promote tumor development by producing anti-inflammatory cytokines, such as IL-4, IL-10, IL-13, and TGFβ, providing an immunosuppressive microenvironment that promotes tumor immune escape." (PMID 33406733, 2021). "In the MMTV-PyMT mice, the levels of type 2 inflammation cytokines such as IL-4 (PE) and IL-13 (serum) increased with tumor progression." (PMID 34707103, 2021). "The expression levels of CXCL10, IGF1, MMP3, MMP1, ICAM1, and IL-13 were significantly up-regulated in tumor tissues." (PMID 34544905, 2021). "Another cytokine recently discovered to be secreted by chronically activated MAIT cells is IL-13, which has properties similar to IL-17, in that IL-13 can also promote tumor growth and is an important player in tissue repair." (PMID 33805904, 2021). "Development of new DIPG tumor nodules both within the pons and throughout the CNS is critical to disease progression and mortality, thus we also investigated the effect of IL-13 stimulation on the invasive potential of DIPG/GBM cell models." (PMID 34001278, 2021). "IL13 serves as an immunoregulatory cytokine, which is closely related to cancer genesis by impacting the tumor immune surveillance." (PMID 34544905, 2021). "In the tumor microenvironment, type II NKT cell-induced tumor suppression can be mediated by IL-13 secretion resulting in the activation of TGF-β-secreting MDSCs that inhibit tumor-specific CD8+ T cells or type I NKT cells." (PMID 34072042, 2021). "NAFLD HCC patients have increased levels of IL-13, which can activate myeloid-derived suppressor cells and promote tumor progression by suppressing tumor immunity." (PMID 34691178, 2021). "Following this study, the group engineered second-generation IL13-targeted CAR T cells with a 4-1BB (CD137) co-stimulation domain and a mutated IgG4-Fc linker to improve anti-tumor potency and increase T cell persistence, while improving the safety profile." (PMID 34298615, 2021). "Tumour-promoting M2 macrophages are induced in tumours by specific cytokines including interleukin-4 (IL-4), IL-10, IL-13 and macrophage colony-stimulating factor (M-CSF)." (PMID 34062862, 2021). "Both IL-4 and IL-13, when in excess, have been connected with more aggressive cancers, enhanced metastasis, proliferation, and tumor growth." (PMID 34071442, 2021). "On the other hand, IL-13 binds to IL-13Rα2 with high affinity and can mediate signal transduction through this chain in diseased fibroblasts and tumor cells." (PMID 33591997, 2021). "The cytokines IL-4, IL-5 and IL-13 secreted by Th2 cells have been found to facilitate tumor growth." (PMID 34722304, 2021). "Functionally, PD-1high ILC2s from tumor tissues expressed higher levels of IL-4 and IL-13 regarding both mRNA and protein levels than PD-1low ILC2s." (PMID 34194433, 2021). "In contrast, M2-like TAMs are induced by Th2 cytokines such as IL-4, IL-10, IL-13, and/or M-CSF, and can favor tumor growth and promote TME remodeling by producing growth factors, immunosuppressive factors, pro-angiogenic molecules, and proteases." (PMID 34603327, 2021).
tumor (continued). "Alternatively, TAMs can produce IL-4 and IL-13 influencing a Th2 lymphocytes response, promoting tumor growth." (PMID 34341329, 2021). "Higher expression levels of IL-4 and IL-13 were found in the serum or the tumor homogenates of a CT26 tumor-bearing mouse model." (PMID 33450900, 2021). "For instance, Th2 lymphocyte-derived IL-4 and IL-13 can enhance epidermal growth factor expression in TAMs, which promotes tumor cell metastasis, as well as the suppressive activity of TAMs, which blunts CD8+ T-cell responses to therapy." (PMID 34603327, 2021). "At the tumor site, a complex interplay occurs between TAM, malignant cells and stromal cells, in which stroma-derived and tumor-derived factors, such as IL4, IL-10, IL-13 and TGF-β, cause a shift towards M2 polarization." (PMID 34298810, 2021). "The arrest of the IL-4/IL-13 pathway by neutralizing IL-4 and IL-13 cytokines leads to inhibition of tumor-cell proliferation." (PMID 34948183, 2021). "ARG1 is induced in tumour-infiltrating myeloid cells such as TAMs, MDSCs, and DCs through the secretion of tumour-derived factors and metabolites, including IL-4, IL-13, IL-6, M-CSF, GM-CSF, TGF-β, and cAMP." (PMID 34685679, 2021). "M2 TAMs secrete pro-tumor factors (IL-4, IL-6, IL-10, IL-13, EGF, and VEGF), while tumor suppressor M1 TAMs express antitumor factors (IL-12, major histocompatibility complex (MHC) class II, and TNF-α)." (PMID 34341329, 2021). "As a tumor develops, the enrichment of IL-4 and IL-13 produced by tumor cells and CD4+ T cells in the TME results in the polarization of TAMs towards an immunosuppressive phenotype, that promotes tumor growth, malignancy, and metastasis." (PMID 34112755, 2021). "IL-13 can promote survival of certain types of tumours through direct action on the tumour or acting through suppression of immuno-surveillance." (PMID 34048465, 2021). "We also found that the protein levels of IL-4 and IL-13 of ILC2s from NSCLC tumor tissues were higher than those from NSCLC PBMCs." (PMID 34194433, 2021). "IL-13 sequestration by IL13α2 within tumour cells results in tumour cell escape from apoptosis, while knocking down IL13Rα2 promotes GBM cell apoptosis." (PMID 34868634, 2021). "Tumor-associated macrophages (TAMs) expressing M2 (alternatively activated)-like phenotype imitate type II T-helper cells that express interleukin (IL)-4, IL-5, IL-6, IL-13, and IL-10 to suppress anti-tumor immune response." (PMID 34831357, 2021). "M2 macrophages meanwhile exert an immunosuppressive phenotype, favoring tissue repair and tumor progression; they secrete anti-inflammatory cytokines such as IL-10, IL-13, and IL-4 along with expressing CD206." (PMID 34917263, 2021). "M2 macrophages, which are activated by the stimulation of IL-4, IL-13, or IL-21, are involved in wound repair, homeostasis, and tumor metastasis and tumor promotion." (PMID 33866463, 2021). "Studies have shown that tumour-derived IL-4, IL-5, IL-6, IL-10, and IL-13 can stimulate TAM polarization towards TAM-M2." (PMID 34141479, 2021). "Much remains to be discovered on the role of IL-13 in tumor beds including processes of macrophage polarization and efferocytosis." (PMID 33922465, 2021). "Th2-related cytokines (IL-4 and IL-13) regulate M2-like macrophages polarization which play a role in promoting tumor progression by creating an immunosuppressive environment." (PMID 34194433, 2021). "As expected, IL-4 and IL-13 levels were highly increased in ILC2s from PBMCs (IL-4, P<0.0001; IL-13, P<0.0001) and tumor tissues (IL-4, P<0.0001; IL-13, P<0.0001) of NSCLC patients than in ILC2s from HD PBMCs." (PMID 34194433, 2021). "It is proposed that this sequestration can be an apoptosis escape mechanism for tumor cells induced by IL-13." (PMID 33591997, 2021). "On the other hand, M2 or alternatively activated macrophages are typically activated by IL-4, IL-13 and IL-10, express IL-10 and favor wound healing as well as tumor development by suppressing anti-tumor T cell responses." (PMID 33494181, 2021).
tumor (continued). "For certain genes (Il10, Csf3, Cxcl1, Ccl2, Gata3, Il5, and Il13), there was a clear difference between the EC and HC Shb KO effects using Cdh5-CreERt2 or Vav1-Cre tumor-bearing mice, indicating that these effects reflect EC cell autonomy of Shb gene deletion." (PMID 34768912, 2021). "IL-4 and IL-13 can display a stimulating influence on tumor progression and metastasis through interactions with various cells in the TME including TAMs." (PMID 33804263, 2021). "IL4 and IL13 were highly expressed in ILC2s obtained from tumor tissues (IL4, P<0.0001; IL13, P<0.0001) and PBMCs (IL4, P<0.0001; IL13, P<0.0001) obtained from NSCLC patients than those obtained from HDs." (PMID 34194433, 2021). "Alternatively, activated macrophages (M2) are stimulated by IL-4 and IL-13 and are involved in tissue repair, suppression of inflammation and tumor progression by secreting the anti-inflammatory cytokines IL-10 and TGF-β." (PMID 32184778, 2020). "The results showed a high positive expression of IL-13 in high-grade cancer tissues compared to tissues from benign tumors, which confirmed that IL-13 is involved in tumor progression." (PMID 33343662, 2020). "M2 macrophages, alternatively induced by Th2 cytokines (interleukin [IL]-4 and IL-13), act as a powerhouse for tumor angiogenesis and metastasis." (PMID 32512803, 2020). "The IL-4 and IL-13 signaling mediate biological effects, such as tumor proliferation, cell survival, cell adhesion and metastasis." (PMID 33233582, 2020). "The protumor activity of ILC2s is mainly attributed to IL-33-driven IL-4 and IL-13 production from these cells which have been reported to support tumor development and progression." (PMID 33233582, 2020). "Other actions of ILC2-derived IL-13 are M2 polarization of tumor macrophages and the activation of MDSCs." (PMID 33138017, 2020). "During tumor development, an increased expression of IL-4R, IL-4 as well as IL-13 and its high affinity receptor IL-13Rα2 are detected in some epithelial cancers, including CRC." (PMID 33371444, 2020). "On the contrary, Th2 cells secrete pro-tumoral cytokines, such as IL-4, IL-5, IL-6, IL-10, and IL-13, which induce anergy in T cells and promote the activities of tumor-promoting macrophages." (PMID 33322132, 2020). "Interleukins (IL)-4 and IL-13 are among the immunomodulatory cytokines believed to play a prominent role in tumor immunity." (PMID 32512917, 2020). "They differentiate from circulating monocytes after migrating into tumor tissue upon stimulation with IL-4, IL-10, or IL-13 and exhibit pro-tumorigenic functions." (PMID 32184778, 2020). "In this model, IL-13 derived from tumor-activated ILC2s was suggested to directly induce MDSC with suppressive activity on antitumor T cell response, as confirmed by MDSC reduction upon partial ILC2 depletion." (PMID 33233582, 2020). "M1 macrophages also amplify Th1 responses, providing a positive feedback loop in anti-tumor response, while M2 macrophages (“healing” phenotype) are mainly stimulated by interleukin-4 (IL-4) or IL-13, inclined to facilitate tumor growth and progression." (PMID 32002338, 2020). "And mature DCs then promote Th2 differentiation of naïve CD4 T cells and induce CD4+ T cells to secrete type 2 cytokines such as IL-13, contributing to tumor development." (PMID 32351590, 2020). "On the contrary, CD4+ TH2, producing IL-4, IL-5, and IL-13, generally promote tumor growth and development." (PMID 32235370, 2020). "The combined treatment with Ccl2 and Il13 increased macrophage infiltration at both the orthotopic primary tumor in the liver and pulmonary metastases (p<0.0001), with enrichment of M2-like Cd206+ TAMs." (PMID 31933479, 2020). "In this study, in the orthotopic-mice model of HCC, YPF increased the levels of Th1 cytokines (IL-2, IL-12, TNF-α, and IFN-γ), decreased the levels of Th2 cytokines (IL-4, IL-5, IL-10, and IL-13), and increased the Th1/Th2 ratio in tumor and adjacent tissues." (PMID 32351590, 2020).